ZDHHC20 (zDHHC palmitoyltransferase 20)
Description:
Palmitoyltransferase that could catalyze the addition of palmitate onto various protein substrates. Catalyzes palmitoylation of Cys residues in the cytoplasmic C-terminus of EGFR, and modulates the duration of EGFR signaling by modulating palmitoylation-dependent EGFR internalization and degradation. Has a preference for acyl-CoA with C16 fatty acid chains. Can also utilize acyl-CoA with C14 and C18 fatty acid chains. May palmitoylate CALHM1 subunit of gustatory voltage-gated ion channels and modulate channel gating and kinetics. Palmitoylates TRIM28 and thereby plays an important role in the DNA damage repair response. (Microbial infection) Dominant palmitoyltransferase responsible for lipidation of SARS coronavirus-2/SARS-CoV-2 spike protein. Through a sequential action with ZDHHC9, rapidly and efficiently palmitoylates spike protein following its synthesis in the endoplasmic reticulum (ER). In the infected cell, promotes spike biogenesis by protecting it from premature ER degradation, increases half-life and controls the lipid organization of its immediate membrane environment. Once the virus has formed, spike palmitoylation controls fusion with the target cell.
Synonyms: DHHC20; FLJ25952; 4933421L13Rik; DHHC-20
Tractability: Small molecule: a structure with a bound ligand is known. Antibody: UniProt places it where antibodies can reach, with high confidence; its Gene Ontology location is reachable by antibodies, with high confidence; UniProt predicts a signal peptide or a membrane-spanning region; the Human Protein Atlas places it where antibodies can reach. PROTAC: ubiquitination databases record sites on it; its protein half-life has been measured; a small molecule that binds it is known.
Target class: Enzyme; Transferase
Gene: Protein-coding gene on chromosome 13 (21,348,784 to 21,459,467, reverse strand). Ensembl gene ENSG00000180776.
Subcellular location: Golgi apparatus membrane; Cell membrane; Cytoplasm, perinuclear region; Endoplasmic reticulum membrane; Endoplasmic reticulum-Golgi intermediate compartment membrane
Subcellular location (Human Protein Atlas): Plasma membrane; Vesicles
Pathways (Reactome):
Disease: Maturation of spike protein
Gene Ontology:
Molecular function: palmitoyltransferase activity; protein-cysteine S-myristoyltransferase activity; protein-cysteine S-palmitoyltransferase activity; protein-cysteine S-stearoyltransferase activity; zinc ion binding
Biological process: DNA damage response; host-mediated activation of viral process; protein maturation; protein targeting to membrane; synaptic vesicle maturation
Cellular component: Golgi membrane; membrane; nucleus; plasma membrane; cytoplasmic vesicle membrane; endoplasmic reticulum; endoplasmic reticulum membrane; endoplasmic reticulum-Golgi intermediate compartment membrane; perinuclear region of cytoplasm
Genetic constraint (gnomAD): Loss-of-function variants: 23 observed, 32.17 expected, observed/expected ratio (o/e) 0.71, 90% interval 0.51 to 1.01. The upper end of that interval is the gene's LOEUF score, 1.01, which puts it in group 4 of 6, group 1 being the genes least tolerant of losing a copy. Missense variants: 287 observed, 310.81 expected, observed/expected ratio (o/e) 0.92, 90% interval 0.84 to 1.02. Synonymous variants: 118 observed, 115.28 expected, observed/expected ratio (o/e) 1.02, 90% interval 0.88 to 1.19.
Homologues: Orthologues: macaque ZDHHC20 (99% identical), dog ZDHHC20 (95% identical), mouse Zdhhc20 (92% identical), rat Zdhhc20 (92% identical), pig ZDHHC20 (91% identical), rabbit ZDHHC20 (89% identical), chimpanzee ZDHHC20 (87% identical), guinea pig ZDHHC20 (79% identical), zebrafish zdhhc20b (64% identical), zebrafish zdhhc20a (63% identical), Drosophila melanogaster CG1407 (46% identical), tropical clawed frog slc66a1l (38% identical), and 8 more. Paralogues in human: ZDHHC2 (62% identical), ZDHHC15 (50% identical), ZDHHC14 (22% identical), ZDHHC3 (20% identical), ZDHHC7 (20% identical), ZDHHC18 (20% identical), ZDHHC9 (19% identical), ZDHHC1 (18% identical), ZDHHC6 (18% identical), ZDHHC12 (16% identical), ZDHHC4 (15% identical), ZDHHC19 (15% identical), and 5 more.
Diseases named in the same sentence as ZDHHC20 in open-access papers:
ZDHHC20 is named in the same sentence as 17 diseases in open-access papers, as found by Europe PMC text mining. Sharing a sentence is not in itself a finding about the gene and the disease. The quoted sentences say what the papers report.
lung carcinoma (5 papers, 2021 to 2025). "By using a KrasG12D-induced spontaneous lung cancer mouse model and Zdhhc20 knockout mice, researchers demonstrated that the ablation of ZDHHC20 or induction of EGFRC1025A mutant inhibited tumorigenesis, which seems contradictory to the increased EGFR activation." (PMID 36577755, 2022). "Studies have shown that the ZDHHC20 expression was elevated in breast and lung cancer cell lines in which epidermal growth factor receptor (EGFR) signaling is present, which implied that ZDHHC20 might play a key role in signal regulation during oncogenesis." (PMID 36286021, 2022).
breast carcinoma (4 papers, 2016 to 2026). "In line with a low expression of DHHC20 in primary tumors compared to lung metastases of mice and patients with breast cancer, we found that Zdhhc20 silencing did not change primary tumor growth in mice." (PMID 41826695, 2026).
pancreatic cancer (3 papers, 2024 to 2025). "To further investigate whether KRAS mutations result in high expression of ZDHHC20 in pancreatic cancer tissues, we treated pancreatic cancer cells with a KRAS G12D inhibitor." (PMID 38821916, 2024). "Through shRNA screening, ZDHHC20 was identified as being essential for pancreatic cancer metastasis." (PMID 40681504, 2025). "ZDHHC20, upregulated by KRAS, is abnormally overexpressed and associated with poor prognosis in patients with pancreatic cancer." (PMID 38821916, 2024). "Dysregulation of ZDHHC20 promotes pancreatic cancer progression in a palmitoylation-dependent manner." (PMID 38821916, 2024). "Further analysis of the GSE16515 dataset showed consistently increased mRNA levels of ZDHHC20 in pancreatic cancer specimens." (PMID 38821916, 2024). "Our data showed higher protein and mRNA levels of ZDHHC20 in pancreatic cancer tissues than in NATs." (PMID 38821916, 2024). "Taken together, our data indicate that ZDHHC20-mediated palmitoylation of YTHDF3 on Cys474 promotes pancreatic cancer progression." (PMID 38821916, 2024). "The expression of ZDHHC20 in pancreatic cancer cell lines was significantly higher than that in normal pancreatic epithelial tissues." (PMID 38821916, 2024). "The CCK8 assay, colony formation assay and Transwell assay results suggested that ZDHHC20 silencing profoundly decreased the proliferation, invasion and migration of these pancreatic cancer cell lines." (PMID 38821916, 2024). "Here, the authors report that ZDHHC20-mediated S-Palmitoylation of the m6A reader YTHDF3 stabilizes MYC mRNA to promote the progression of KRAS-mutant pancreatic cancer." (PMID 38821916, 2024). "To investigate the specific mechanisms by which ZDHHC20 regulates pancreatic cancer progression, we conducted immunoprecipitation–tandem mass spectrometry (IP-MS) to identify potential binding partners of ZDHHC20." (PMID 38821916, 2024). "High expression levels of ZDHHC20 were obviously correlated with unfavorable prognosis in patients with pancreatic cancer." (PMID 38821916, 2024). "We next examined the mRNA and protein expression levels of ZDHHC20 in pancreatic cancer tissues and NATs collected from our hospital." (PMID 38821916, 2024). "Our findings reveal the regulatory role of ZDHHC20 in the occurrence and development of pancreatic cancer." (PMID 38821916, 2024). "Expression of the two mutants considerably decreased the catalytic palmitoylation activity of ZDHHC20 and inhibited the proliferation and invasion of pancreatic cancer cells." (PMID 38821916, 2024). "To elucidate the mechanism by which the ZDHHC20–YTHDF3 axis promotes the progression of pancreatic cancer, we carried out RNA-seq analysis in PANC-1 cells with ZDHHC20 silencing." (PMID 38821916, 2024). "Dysregulation of ZDHHC20 expression promotes pancreatic cancer progression in a palmitoylation-dependent manner." (PMID 38821916, 2024). "Given the abnormal expression of ZDHHC20 in pancreatic cancer tissues, we next explored the biological function of ZDHHC20 in pancreatic cancer cells." (PMID 38821916, 2024). "The results of RT‒qPCR and western blot analyses showed that KRAS G12D inhibitor treatment significantly downregulated ZDHHC20 expression in pancreatic cancer cells." (PMID 38821916, 2024). "In conclusion, ZDHHC20, upregulated by KRAS, is abnormally overexpressed and associated with poor prognosis in patients with pancreatic cancer." (PMID 38821916, 2024). "Similarly, another study revealed that ZDHHC20 is abnormally increased in pancreatic cancer tissues and is related to poor prognosis." (PMID 40681504, 2025). "Notably, we found that YTHDF3 protein levels were downregulated in ZDHHC20-KO pancreatic cancer cells, and the knockdown of HSC70 or LAMP2A reversed the effects of ZDHHC20 deficiency on YTHDF3 protein levels in ZDHHC20-KO cells." (PMID 38821916, 2024).
pancreatic cancer (continued). "Furthermore, to fully understand the biological role of ZDHHC20 and YTHDF3 in pancreatic cancer, future studies using pancreas-specific deficiency of ZDHHC20 or YTHDF3 KPC mice model are warranted." (PMID 38821916, 2024). "This may suggest that STAT3 plays a promoting role in pancreatic cancer progression, perhaps in part by inducing overexpression of ZDHHC20." (PMID 38821916, 2024). "We next investigated whether ZDHHC20 promotes pancreatic cancer progression by affecting the biological function of MYC." (PMID 38821916, 2024). "Thus, we carried out the dual-luciferase reporter assay in pancreatic cancer cells and found that 2-BP treatment or ZDHHC20 knockout significantly downregulated the Fluc activity of the wild-type reporter." (PMID 38821916, 2024). "Together, these results indicate that ZDHHC20 functions as a tumor promoter in pancreatic cancer." (PMID 38821916, 2024). "Based on the positive effect of the ZDHHC20–YTHDF3 axis on pancreatic cancer progression, we next explored whether palmitoylation of Cys474 plays a key role in this process." (PMID 38821916, 2024). "ZDHHC20 overexpression promoted pancreatic cancer cell proliferation, invasion and migration." (PMID 38821916, 2024). "Moreover, knockdown or inhibition of STAT3 significantly reduced ZDHHC20 expression, overexpression of STAT3 resulted in significantly upregulation of ZDHHC20 in pancreatic cancer cells." (PMID 38821916, 2024). "Furthermore, our TIMER database analysis revealed that ZDHHC20 expression levels were higher in tumor tissues from pancreatic cancer patients harboring KRAS mutations than in those without KRAS mutation." (PMID 38821916, 2024). "Hence, these results suggest that ZDHHC20 may promote pancreatic cancer progression in a manner at least partially dependent on palmitoylation." (PMID 38821916, 2024). "In pancreatic cancer (GSE16515 dataset), ZDHHC20 mRNA is overexpressed compared to normal tissues (Fold Change = 1.004), and high ZDHHC20 expression correlates with worse survival in pancreatic and liver cancer patients." (PMID 40335986, 2025). "In the present study, we discover that ZDHHC20, a protein upregulated by KRAS, is abnormally overexpressed and predict an unfavorable prognosis in pancreatic cancer." (PMID 38821916, 2024). "Therefore, we further explored whether ZDHHC20 promotes pancreatic cancer progression via YTHDF3." (PMID 38821916, 2024). "The protein level of ZDHHC20 was additionally evaluated by immunohistochemical staining in a tissue microarray containing tumor tissue and NAT specimens from 29 pancreatic cancer patients." (PMID 38821916, 2024). "Further, we design a biologically active YTHDF3-derived peptide to competitively inhibit YTHDF3 palmitoylation mediated by ZDHHC20, which in turn downregulates MYC expression and inhibits the progression of KRAS mutant pancreatic cancer." (PMID 38821916, 2024). "This posttranslational modification is regulated by ZDHHC20 and maintains the protein stability of YTHDF3, which is essential in the development of pancreatic cancer." (PMID 38821916, 2024). "Mechanistically, ZDHHC20 facilitates the palmitoylation of YTHDF3 at Cys474 via STAT3, which enhances the stability of MYC mRNA, thereby driving the proliferation and invasion of pancreatic cancer." (PMID 40681504, 2025). "When analyzing ZDHHC20 in pancreatic cancer tissues compared to adjacent nontumor tissues, we found that the protein expression difference of ZDHHHC20 by IHC is more significant than the mRNA expression difference from the GSE16515 dataset." (PMID 38821916, 2024). "In addition, bioinformatic analysis showed a positive correlation between ZDHHC20 and STAT3 mRNA levels in various cancers, including pancreatic cancer." (PMID 38821916, 2024).
lung adenocarcinoma (2 papers, 2021 to 2022). A carcinoma that arises from the lung and is characterized by the presence of malignant glandular epithelial cells. "Expression analysis of ZDHHC20 mRNA from lung adenocarcinoma patients using the PRECOG portal correlates high ZDHHC20 mRNA expression with lower survival probability (Z-score 3.19)." (PMID 34610265, 2021). "Our in vivo studies demonstrate that ablating the gene Zdhhc20 by CRISPR/Cas9-mediated inhibition in a mouse model of oncogenic Kras-driven lung adenocarcinoma potently inhibits tumorigenesis." (PMID 34610265, 2021). "Blocking zDHHC20-mediated EGFR S-acylation has also been shown to reduce PI3K signaling and MYC levels and suppress cell growth in vitro and tumor growth in an in vivo model of KRAS-mutant lung adenocarcinoma." (PMID 36087837, 2022).
pancreatic ductal adenocarcinoma (2 papers, 2025 to 2026). An infiltrating adenocarcinoma that arises from the epithelial cells of the pancreas. "In pancreatic ductal adenocarcinoma (PDAC), KRAS signaling upregulates ZDHHC20 expression in KPC mouse models, with its overexpression correlating with poor patient prognosis." (PMID 40977744, 2025). "In pancreatic ductal adenocarcinoma (PDAC), the palmitoyltransferase ZDHHC20 promotes metastatic outgrowth by palmitoylating unidentified substrate(s), an effect dependent on NK cell-mediated immune evasion mechanisms." (PMID 40977744, 2025).
Alzheimer disease (1 paper, 2022). A progressive, neurodegenerative disease characterized by loss of function and death of nerve cells in several areas of the brain leading to loss of cognitive function such as memory and language. "Interestingly, both ZDHHC20 and ZDHHC21 have a potential role in the pathogenesis of Alzheimer’s disease, as they can palmitoylate BACE1, Tau and amyloid precursor protein." (PMID 35819139, 2022).
colitis (1 paper, 2023). Inflammation of the colon. "The expression of ZDHHC20Long is also triggered following chemically induced colitis and pore-forming toxins, suggesting that the transcriptional regulation of ZDHHC20 is part of a “damage” response pathway." (PMID 37952051, 2023). "We assessed ZDHHC20 expression before and after the 10-day colitis experiment." (PMID 37952051, 2023).
liver cancer (1 paper, 2025). An epithelial or non-epithelial malignant neoplasm that arises from the liver. "For example, studies show that ZDHHC3/9 modulates the tumor immune microenvironment by inhibiting PD- 1/L1 ubiquitination, while our lab has found that ZDHHC20 stabilizes FASN by preventing its ubiquitin–proteasome mediated degradation, promoting liver cancer progression." (PMID 40335986, 2025).
pancreatic adenocarcinoma (1 paper, 2026). "DHHC20 has been previously studied in metastatic pancreatic adenocarcinoma, and it was found that Zdhhc20 knockout decreased metastasis in immunocompetent but not natural killer cell-depleted mice." (PMID 41826695, 2026).
schizophrenia (1 paper, 2025). A major psychotic disorder characterized by abnormalities in the perception or expression of reality. "This study unveils a novel causal pathway in schizophrenia, wherein DNA methylation at cg18095732 regulates ZDHHC20 expression, which in turn influences schizophrenia risk through CCR7‐mediated immune modulation." (PMID 40842128, 2025). "Downstream, CCR7 expression on naive CD8+ T cells mediates 33.35% of ZDHHC20’s influence on schizophrenia risk (p < 0.05)." (PMID 40842128, 2025). "Uniquely, our MR approach establishes causality, revealing that DNA methylation at cg18095732 accounts for over half of ZDHHC20’s effect on schizophrenia risk." (PMID 40842128, 2025). "Using MR, this study provides compelling evidence for a novel causal pathway implicating ZDHHC20, a palmitoyltransferase, in schizophrenia pathogenesis." (PMID 40842128, 2025). "We found a significant causal association between increased ZDHHC20 expression, a palmitoyltransferase, and elevated schizophrenia risk (p < 0.05), confirmed by SMR." (PMID 40842128, 2025). "Therapeutic Potential: Identifying ZDHHC20 as a nexus of schizophrenia pathology provides a tangible target for precision medicine." (PMID 40842128, 2025). "We further explored the downstream mechanism by which ZDHHC20 affects schizophrenia through immune cells, employing MR analysis." (PMID 40842128, 2025). "To investigate upstream mechanisms, we conducted MR analysis to assess how DNA methylation at CpG sites influences schizophrenia via the ZDHHC20 palmitoylation gene." (PMID 40842128, 2025). "Using a two‐step MR method with directional filtering of β, β1, and β2, we delineated a pathway connecting ZDHHC20, immune cells, and schizophrenia." (PMID 40842128, 2025). "Our analysis revealed that CCR7 on naive CD8br cells mediates the effect of ZDHHC20 on schizophrenia, with a mediation effect of 0.0634, accounting for 33.35% of the total effect." (PMID 40842128, 2025). "Using a two‐step MR approach with directional filtering of regression coefficients (β, β1, and β2), we identified a potential pathway linking DNA methylation CpG sites, ZDHHC20, and schizophrenia." (PMID 40842128, 2025). "After calculating the mediation effect, we found that ZDHHC20 mediates the impact of the DNA methylation CpG site cg18095732 on schizophrenia, with a mediation effect of 0.0383, representing 59.31% of the total effect." (PMID 40842128, 2025). "This study reveals a novel mechanistic axis in schizophrenia: DNA methylation‐ZDHHC20‐immune regulation, linking epigenetic modifications and palmitoylation to neuroimmune dysregulation." (PMID 40842128, 2025). "We aim to examine DNA methylation's role in regulating ZDHHC20 and its downstream effects on immune cell activity in schizophrenia." (PMID 40842128, 2025). "Upstream, DNA methylation at cg18095732 regulates ZDHHC20, mediating 59.31% of its effect on schizophrenia (p < 0.05)." (PMID 40842128, 2025). "Specifically, we will investigate how DNA methylation in genes like ZDHHC20 influences immune‐mediated processes leading to schizophrenia onset." (PMID 40842128, 2025).